CD38 (CD38 molecule)
Diseases named in the same sentence as CD38 in open-access papers (continued):
Sharing a sentence is not in itself a finding about the gene and the disease.
lymph node metastasis (9 papers, 2016 to 2026). "The level of CD38 + NK cells was linked to poor prognosis as well as lymph node metastasis." (PMID 41530841, 2026). "Patients with high CD38 expression in TCs (CD38(TCs)) had higher TNM stages and an increased risk of lymph node metastasis." (PMID 39192980, 2024). "Patients with highly expressed CD38 in TCs (CD38TCs) had higher TNM stage and risk of lymph node metastasis." (PMID 34211854, 2021). "There are a negative correlation for CD4+ T‐cell counts and positive correlation for percentages of CD8+ HLA‐DR/CD8+ T cell and CD8+ CD38+/CD8+ T cells with the lymph node metastasis." (PMID 32459060, 2020). "CD8+CD38+ showed significant correlation with lymph node metastasis." (PMID 32050977, 2020). "Furthermore, PTC group with lymph node metastasis showed more CD8+CD38+ coexpression than those in the TN group." (PMID 32050977, 2020). "CD8+CD38+ showed a significant correlation with lymph node metastasis." (PMID 32050977, 2020). "Similarly, 6 out of 8 lymph node metastases and 10 out of 12 distant metastases showed methylation of CD38." (PMID 30258629, 2018). "CD8+CD38+ cells might act as a novel predictor of lymph node metastasis in patients with PTC." (PMID 32050977, 2020). "In this study, we discovered that CD8+ HLA‐DR+/ CD8+ and CD8+ CD38+/CD8+ percentage was positively correlated with cancer stage, tumor stage, lymph node metastasis, and distant metastasis." (PMID 32459060, 2020). "There was a decrease in the lymph node metastasis‐related trend of CD4+ T‐cell counts (F = 3.537, P = .004), but an increased lymph node metastasis‐related trend of CD8+ HLA‐DR/ CD8+ T‐cell percentages (F = 4.247, P = .001) and CD8+ CD38+/CD8+ T cells (F = 10.984, P < .001)." (PMID 32459060, 2020).
multiple sclerosis (9 papers, 2020 to 2024). A progressive autoimmune disorder affecting the central nervous system resulting in demyelination. "In astrocytes, CD38 was increased around lesions caused by lysolecithin or multiple sclerosis, and loss of CD38 significantly slowed demyelination." (PMID 39273079, 2024). "Activated memory B-cells with intermediate and high expression of CD38 are susceptible to fingolimod, so their decrease is observed after the course of the treatment of multiple sclerosis." (PMID 36077708, 2022). "In multiple sclerosis (MS), CD38+ memory B-cell in the blood migrate toward the central nervous system by expressing the adhesion molecule ALCAM." (PMID 37144136, 2023). "In the experimental autoimmune encephalomyelitis mouse model of multiple sclerosis, CD38 deletion reduced disease severity." (PMID 32085567, 2020). "The immunosuppressive effect of anti-CD38 antibodies on plasma cells and plasmablasts could be also useful against autoimmune neurological disorders such as multiple sclerosis." (PMID 36077708, 2022). "Furthermore, after fingolimod application, the proportion of regulatory B-cells (CD38+CD27−CD24+CD5+) is significantly increased as compared to treatment-naïve multiple sclerosis patients and healthy controls, and significantly more of them produce IL-10." (PMID 36077708, 2022). "The immunosuppressive effect of anti-CD38 antibodies like daratumumab on plasma cells and plasmablasts could be useful against autoimmune neurological disorders like multiple sclerosis." (PMID 32085567, 2020). "Finally, other studies have uncovered the role of CD38 in chronic autoimmune diseases, such as inflammatory bowel disease and multiple sclerosis, through various mechanisms, and studies evaluating the efficacy of daratumumab in these patient populations may be warranted." (PMID 38233570, 2024).
plasmacytoma (9 papers, 2018 to 2025). Plasmacytoma is a localized mass of neoplastic monoclonal plasma cells that represents approximately 5% of all plasma cell neoplasms. "CD38‐EVs had significantly lower lung retention than EVs in plasmacytoma‐bearing mice, similar to normal C57BL/6J mice." (PMID 40317915, 2025). "The findings demonstrate that MNs are superior to i.v administration for delivering CD38‐EVs‐Dox in plasmacytoma therapy." (PMID 40317915, 2025). "The collective data demonstrate the advantages of the targeted and site‐specific antitumour efficacy of CD38‐EVs‐DoxMNs in plasmacytoma‐bearing mice." (PMID 40317915, 2025). "The plasmacytoma‐bearing mice received various treatments: i.v EVs‐Dox and CD38‐EVs‐Dox (EVs‐Doxi.v and CD38‐EVs‐Doxi.v), MN‐delivered EVs‐Dox and CD38‐EVs‐Dox (EVs‐DoxMNs and CD38‐EVs‐DoxMNs), with PBS as the negative control." (PMID 40317915, 2025). "The engineered CD38‐EVs acquired a positive surface charge, which likely enhanced their access to plasmacytoma sites." (PMID 40317915, 2025). "Our findings demonstrated that MNs encapsulated with CD38‐EVs provide a more effective method for engineered EVs delivery to treat plasmacytoma in mice compared to i.v administration." (PMID 40317915, 2025). "CD38‐EVs‐DoxMNs have superior efficacy and safety in treating plasmacytoma mice, compared to CD38‐EVs‐Doxi.v, providing novel insights into the potential of MNs as a platform for delivering targeted engineered EVs in tumour therapy." (PMID 40317915, 2025). "We evaluated the safety profile of CD38‐EVs‐DoxMNs by examining skin tolerability, monitoring body weight and measuring liver and kidney function in plasmacytoma‐bearing mice." (PMID 40317915, 2025). "We then created plasmacytoma‐bearing NOD/SCID mouse models by injecting CD38‐EVs via the tail and used the FMP imaging system to observe tumour tissues in vivo and ex vivo." (PMID 40317915, 2025). "A schematic illustration of engineered EVs (CD38‐EVs‐Dox) delivered via MNs or intravenous administration for plasmacytoma treatment." (PMID 40317915, 2025). "Plasmacytomas are histologically the same as MM, with tumors showing predominantly plasma cells that stain positively for CD38 and CD138 with the majority having immunoglobulin light-chain restriction." (PMID 38983538, 2022). "Our patient had MM with plasmacytoma with bone marrow involvement of 31%, with high expression of CD38 and CD56, and multiple bone lytic lesions on X-rays confirmed with a CT scan." (PMID 29549883, 2018). "However, CD38‐EVs were notably more concentrated in the spleen of plasmacytoma‐bearing mice." (PMID 40317915, 2025). "In this study, we used plasmacytoma‐bearing NOD/SCID mice as tumour models and developed CD38 peptide‐engineered EVs (CD38‐EVs) from umbilical cord MSCs to target malignant plasma cells." (PMID 40317915, 2025). "In our plasmacytoma‐bearing NOD/SCID mouse models, we employed MNs to deliver CD38‐EVs, which exhibited improved targeting and delivery to tumour sites compared to standard EVs." (PMID 40317915, 2025). "Plasmacytomas of the clear cell type that express the post-germinal centre and plasma cell markers MUM-1, CD138, CD38, kappa, lambda and MUC-1." (PMID 39465766, 2024). "Sternum puncture confirmed plasmacytoma, with immunohistochemistry showing plasma cell origin: CD20-, CD3-, CD38+, LCA-, Ki67 + 20%, MUM1+, CD56-, CyclinD1-, CD117-, κ+, λ-." (PMID 39139556, 2024). "Plasma cells in solitary plasmacytoma will be positive for CD138, CD38, and show light chain restriction (stain positive for either kappa or lambda but not both)." (PMID 37303483, 2023).
plasmacytoma (continued). "Histopathology demonstrated diffuse infiltration of atypical plasma cells consistent with plasmacytoma, supported by immunohistochemical positivity for CD138, CD38, MUM1, and CD56, and an elevated serum β2-microglobulin level, confirming the diagnosis of MM with hepatic involvement." (PMID 41001027, 2025). "In plasmacytoma NOD/SCID mouse models, CD38‐EVs encapsulated within MNs (CD38‐EVsMNs) effectively targeted the tumour cells much more than the standard EVs encapsulated within MNs (EVsMNs) and CD38‐EVs intravenously administrated (CD38‐EVsi.v), with reduced distribution to the lungs and spleen." (PMID 40317915, 2025). "Immunohistochemistry in this case was negative for CD138, kappa, lambda and MUC-1, although CD38 and MUM-1 were expressed, still ruling out a plasmacytoma." (PMID 39465766, 2024). "While there is a lack of data about activity of anti-CD38 antibodies in the NDMM patients with plasmacytomas, data from RRMM patients with plasmacytomas are not promising." (PMID 36289797, 2022).
Waldenstrom macroglobulinemia (9 papers, 2012 to 2024). "A considerable amount of malignant clone of plasma cells in Waldenström macroglobulinemia patients expresses CD38 (40–70%), explaining the rationale for a recently completed clinical trial to treat Waldenström macroglobulinemia patients with daratumumab." (PMID 36139103, 2022).
colon cancer (8 papers, 2013 to 2025). "The results showed the LNM in both colon cancer and rectal cancer was associated with tumor size, histologic grade, depth of invasion, LVI, perineural invasion, CEA, and CD38+ NK cells; Besides, LNM in rectal cancer was also associated with neoadjuvant therapy." (PMID 38463232, 2024). "Taken together, these mechanisms may contribute to reduced CD38-mediated adenosine production, an improved host anti-tumor immune response, and the observed synergy between PD-1 blockade and a CD38-targeting antibody in the murine colon cancer model." (PMID 33321969, 2020). "A CD38+ myeloid-derived suppressor cell (MDSC) population has been reported in pro-metastatic models and patients with advanced-stage head and neck and colon cancer." (PMID 40327401, 2025). "CD38, which liberates nicotinamide from NADP+, may also be responsible for the observed lowering of the cellular NADPx content during a preincubation of the cells with thionicotinamide as previously also reported for colon cancer cells." (PMID 41137997, 2025).
endothelial dysfunction (8 papers, 2018 to 2025). In vascular diseases, endothelial dysfunction is a systemic pathological state of the endothelium (the inner lining of blood vessels) and can be broadly defined as an imbalance between vasodilating and vasoconstricting substances produced by (or acting on) the endothelium. "The protective role of CD38 loss of function against oxidative injury and endothelial dysfunction in coronary ischemia/reperfusion was further demonstrated by the pharmacologic administration of potent CD38 inhibitor in additional experiments." (PMID 35712720, 2022). "The activation of CD38 is a significant cause of endothelial dysfunction following ischemia." (PMID 40066352, 2025). "CD38 overactivation may be a potential cause of postischemic endothelial dysfunction, implying that CD38 is a possible target for preventing endothelial dysfunction in CAD." (PMID 38974325, 2024). "Activation of CD38 by hypoxia-reoxygenation depletes NAD(P)+ in cardiac endothelial cells and impairs nitric oxide production by endothelial nitric oxide synthase that utilizes NADPH as the reducing substrate, suggesting that CD38 may cause endothelial dysfunction after ischemic injury." (PMID 32903597, 2020). "Administration of a potent CD38 inhibitor resulted in reversal of endothelial dysfunction and improvement of post ischemic cardiac injury." (PMID 35712720, 2022). "CD38 is highly expressed by endothelial cells, whereas CD38 expression mediates endothelial dysfunction induced by hypoxia-reoxygenation in the heart." (PMID 34680206, 2021). "OxLDL and 3NT stimulated an increase in CD38 that is also described as a prognostic marker in endothelial dysfunction." (PMID 34679610, 2021). "In these models, oxidative stress induced an increase in CD38 enzymatic activity leading to NAD(P)H depletion and endothelial dysfunction." (PMID 35712720, 2022). "In endothelial cells, inhibition of CD38 preserves nitric oxide (NO) synthase activity and NO generation, whereas activation of CD38 leads to NADPH depletion, thereby contributing to endothelial dysfunction in the heart." (PMID 30127733, 2018). "We postulate this hypothesis based on our prior data in coronary ischemia/reperfusion models where we identified that oxidative stress associated with coronary reperfusion results in significant increase in CD38 enzymatic activity and NAD(P)H depletion leading to endothelial dysfunction." (PMID 35712720, 2022).
Glucose intolerance (8 papers, 2015 to 2026). Glucose intolerance (GI) can be defined as dysglycemia that comprises both prediabetes and diabetes. "Despite comparable body weight between HP- and LP-fed in Cd38Lyz2 mice, macrophage CD38 deficiency alleviated HP-induced glucose intolerance, suggesting that macrophage CD38 is critical to systemic metabolic dysregulation." (PMID 41397559, 2026). "CD38 inhibitors enhance glucose intolerance and insulin resistance in mice and lipid accumulation in the liver is greatly decreased in CD38-deficient mice." (PMID 36794157, 2023). "Our unpublished data showed that in type 1 diabetes, the glucose intolerance was improved, whereas the insulin resistance was not changed in CD38-deficient mice." (PMID 37958991, 2023). "The resultant CD38 knockout mice having human CD38 transgene ameliorated the glucose intolerance and the decreased insulin secretion observed in CD38 knockout mice, suggesting that the observed phenotype in CD38 knockout mice is indeed caused by the disruption of the CD38 gene in pancreatic β-cells." (PMID 35457121, 2022). "78c is a specific inhibitor of CD38 and does not directly affect the activity or expression of other enzymes involved in NAD+ metabolism, it could improve glucose intolerance and insulin resistance in mice." (PMID 36794157, 2023).
ischemia (8 papers, 2012 to 2025). A hypoperfusion of the BLOOD through an organ or tissue caused by a PATHOLOGIC CONSTRICTION or obstruction of its BLOOD VESSELS, or an absence of BLOOD CIRCULATION. "In vivo experiments have also demonstrated that the administration of exogenous NAD+ to CD38-deficient mice protects the heart against ischemia/reperfusion and reduces the size of the infarct." (PMID 40529366, 2025). "Pharmacological inhibition of CD38 exerts a cardioprotective effect by reducing endothelial damage post-ischemia." (PMID 34680206, 2021). "Pharmacological inhibition of CD38 by thiazoloquin(az)olin(on)e 78c or miR-499a-5p exerts a cardioprotective effect by reducing endothelial damage post-ischemia." (PMID 34680206, 2021). "Here, we showed that the hearts of CD38 deficient mice or wild type mice supplied with exogenous NAD were significantly protected from ischemia/reperfusion injury, seen as reduction of the myocardial infarct sizes when the mice were subjected to 30 min ischemia followed by 24 hours of reperfusion." (PMID 27547294, 2016). "This study investigates CD38 as a potential regulator of TRPM2, highlighting a novel target to reverse hippocampal synaptic plasticity deficits after ischemia." (PMID 40822706, 2024).
liver fibrosis (8 papers, 2013 to 2025). "The authors found that the proportion CD38+HLA-DR+CD8+ T cells positively correlated with liver fibrosis progression." (PMID 40959088, 2025). "Localization of CD38 in hepatic stellate cells was also confirmed in both livers of patients with liver fibrosis and with chronic hepatitis." (PMID 36012131, 2022). "This is a pathophysiologically relevant mechanism since CD38−/− mice are protected to some extent from liver fibrosis induced by bile duct ligation." (PMID 27903970, 2017). "In hepatocytes, CD38-mediated Ca2+ signaling contributes to angiotensin II-induced activation of hepatic stellate cells, inducing hepatic fibrosis." (PMID 27924060, 2016). "Moreover, the reduced eNAD+ levels observed in patients with liver fibrosis or cirrhosis may be linked to impaired NAD+ biosynthesis, increased NAD+ consumption due to chronic inflammation, and enhanced enzymatic degradation by ectoenzymes such as CD38 or CD203a." (PMID 40107998, 2025). "Differences in expression of activation and exhaustion markers (HLA-DR, CD38, PD-1, Tim-3 and Fas) and phenotypic markers on CD4+ and CD8+ T-cells were analysed by flow cytometry and were related to HCV disease parameters (HCV-viremia, ALT and liver fibrosis)." (PMID 23555014, 2013).
myelodysplastic syndrome (8 papers, 2013 to 2025). A clonal hematopoietic disorder characterized by dysplasia and ineffective hematopoiesis in one or more of the hematopoietic cell lines. "Collectively, these results indicate that about 20% of SCID-Rasa3−/− mice develops a preleukemia with a massive infiltration of bone marrow and spleen with CD117+ Sca-1+ CD38+ cells, probably leading to bone marrow failure and premature death." (PMID 24967784, 2014). "Immunophenotypic profiles of HSPC subpopulations were examined in BM samples of 10 newly diagnosed CD34+/CD38− AML patients, 6 patients with myelodysplastic syndromes (MDS), and 7 healthy donors (HDs)." (PMID 40362463, 2025). "Recently, overexpression of CLL1 by CD34+ CD38- bone marrow fraction and its various subcompartments (HSC, MPP and LMPP) has been demonstrated in patients with MDS-EB (myelodysplastic syndromes with excess blasts), compared to LR-MDS and healthy individuals." (PMID 34490124, 2021).
systemic sclerosis (8 papers, 2019 to 2025). A chronic disorder, possibly autoimmune, marked by excessive production of collagen which results in hardening and thickening of body tissues. "Targeting the CD38 molecule may also bring other therapeutic effects in systemic sclerosis." (PMID 37630981, 2023). "CD38 is upregulated in systemic sclerosis (SSc), a chronic disease characterized by fibrosis in multiple organs." (PMID 38086958, 2023).
Allergy (7 papers, 2017 to 2026). An allergy is an immune response or reaction to substances that are usually not harmful. "Important for the context of allergic diseases is the fact, that CD38+ CD4+ T cells were characterized to be hypo-proliferative with a specific bias towards IL-13 secretion (with no change toward IL-4 or IL-5 secretion)." (PMID 38318168, 2024). "Indeed, mTOR inhibition attenuated OVA-mRNA-LNP–induced CD8+ T cells in the lung and the CD38+KLRG1– CD8+ T cell subset, including perforin production, while preserving the anti-allergy effect of the vaccination." (PMID 40985871, 2025). "In people without allergy, expression level of CD38 was low and only slightly enhanced by stimulation with nickel in cell culture." (PMID 38203472, 2023).
celiac disease (7 papers, 2015 to 2025). An autoimmune genetic disorder with an unknown pattern of inheritance that primarily affects the digestive tract. "It suggests CD38 expression as an alternative to outcome measures concerning celiac disease patients." (PMID 36077708, 2022). "In celiac diseases, CD38 expression on gluten-specific T cells augments remarkably." (PMID 36077708, 2022). "This study also showed that CD38 was up-regulated in children with celiac disease." (PMID 27483138, 2016). "We speculate that the lower percentage of CD38+ memory B cells seen in children with C in comparison to the other study groups partly can depend on the discrepancy in gluten challenge ‘status’ and celiac disease duration." (PMID 38134245, 2024). "Consistent with this notion, activated (CD38+) and gut-homing (CD103+) IELs re-enter the bloodstream upon gluten challenge in patients with celiac disease." (PMID 36326697, 2023). "In peripheral blood, CD38 expression on pre-activated CD62Llow CD4+ T cells correlates with CCR9 and particularly with β7-integrin expression, and gliadin-specific CD4+ T cells from patients with celiac disease are homogenously CD38+." (PMID 25938500, 2015).